PTBP1 (polypyrimidine tract binding protein 1)
Diseases named in the same sentence as PTBP1 in open-access papers (continued):
Sharing a sentence is not in itself a finding about the gene and the disease.
leukemia (3 papers, 2021 to 2026). A malignant (clonal) hematologic disorder, involving hematopoietic stem cells and characterized by the presence of primitive or atypical myeloid or lymphoid cells in the bone marrow and the blood. "Previous work has implicated PTBP1 in the regulation of glycolysis by altering the splicing of pyruvate kinase (PKM) in leukemia." (PMID 41214140, 2026). "Functional categorization and overrepresentation analysis of Kegg pathways revealed that the genes downregulated with PTBP1 KD are associated with metabolic pathways critical for leukemia cell growth, including pyruvate metabolism and glycolysis." (PMID 41214140, 2026). "We observed a significant increase in the Annexin V+ population in shPTBP1 cells as compared to control, indicating that loss of PTBP1 sensitizes leukemia cells to chemotherapy." (PMID 41214140, 2026). "In leukemia, PTBP1 has been linked to leukemia cell survival, metabolism, and progression." (PMID 41214140, 2026). "For this, we used mouse CM+ leukemia cells expressing GFP from the Rosa26 locus (CM+, GFP+), and took advantage of the natural variability in PTBP1 expression levels in primary leukemia cells." (PMID 41214140, 2026). "Based on our data, we propose that the interaction between RUNX1 and PTBP1 facilitates expression of metabolic proteins essential for leukemia cell growth and survival." (PMID 41214140, 2026). "We also performed immunoprecipitations/westerns (IP/WB) using the human CM expressing AML cell line, ME-1, and found that RUNX1 interacts with PTBP1 in human leukemia cells, as well." (PMID 41214140, 2026). "Collectively, these results indicate that PTBP1 regulates the expression of key metabolic genes required for efficient glycolysis and survival in leukemia cells." (PMID 41214140, 2026). "Downregulation of genes associated with glycolysis and pyruvate metabolism with PTPB1 KD implies a role for PTBP1 in regulating leukemia cell growth." (PMID 41214140, 2026). "Our study demonstrates a novel facet of RUNX1’s role in leukemia through its interaction with PTBP1 and the regulation of metabolism." (PMID 41214140, 2026). "Using publicly available gene expression data, we found that PTBP1 is expressed at similar levels in leukemia cells and healthy HSPCs but decreases with differentiation." (PMID 41214140, 2026). "We also show that RUNX1 and PTBP1 co-localize at the promoters of actively transcribed genes, including key metabolic genes, and that loss of PTBP1 decreases expression of target genes, resulting in impaired glycolysis and cell death, linking RUNX1 to the control of metabolism in leukemia." (PMID 41214140, 2026). "To address whether RUNX1 binds PTBP1 in these cells, we compared the expression of PTBP1 in leukemia cells and HSPCs." (PMID 41214140, 2026). "Previous work in genetic mouse models indicates a role for PTBP1 in healthy hematopoietic stem cells, raising the possibility that PTBP1 could also regulate leukemia stem cell (LSC) activity." (PMID 41214140, 2026). "We confirmed the interaction by showing higher co-immunoprecipitation of PTBP1 with RUNX1, compared to IgG, in 3 independent mouse CM+ leukemia samples." (PMID 41214140, 2026). "CM+, GFP+ leukemia cells were sorted for GFP, and WBs were used to identify mouse leukemia samples with PTBP1 expression above (PTBP1 high) and below (PTBP1 low) the median expression level." (PMID 41214140, 2026). "This work supports a model in which recruitment of PTBP1 to RUNX1 target genes promotes their efficient expression and maintains robust glycolytic output, highlighting a previously unrecognized aspect of RUNX1’s central role in leukemia pathogenesis." (PMID 41214140, 2026).
leukemia (continued). "Our findings lead us to propose the following mechanism: PTBP1, which does not have a DNA binding domain, binds RUNX1 and is recruited to the promoter regions to drive expression of genes essential for leukemia cell survival." (PMID 41214140, 2026). "To determine whether disruption of the RUNX1/PTBP1 interaction differentially affected the LSC and non-LSC cells, we treated mouse CM+ leukemia cells with entinostat for 24 h, and examined glucose uptake in these populations." (PMID 41214140, 2026).
liver fibrosis (3 papers, 2021 to 2023). "In conclusion, here we showed that the METTL3/MALAT1/PTBP1/USP8/TAK1 axis was activated in macrophages during the development of liver fibrosis." (PMID 34839365, 2021). "In addition, the METTL3/MALAT1/PTBP1/USP8/TAK1 axis in liver fibrosis promotes pyroptosis and macrophage M1 polarization, thereby exacerbating liver fibrosis progression." (PMID 37063421, 2023). "The signaling cascade METTL3/MALAT1/PTBP1/USP8/TAK1, by essentially stimulating pyroptosis and inflammation of macrophages, aggravates liver fibrosis." (PMID 34839365, 2021). "Our data unveils a lnc-Helf/PTBP1/PIK3R5/AKT feedforward amplifying signaling to exacerbate the process of hepatic fibrosis and inflammation, thus providing a possible therapeutic strategy for hepatic fibrosis." (PMID 37805473, 2023). "Our results unveil a lnc-Helf/PTBP1/PIK3R5/AKT feedforward, amplifying signaling that exacerbates the process of hepatic inflammation and fibrosis, thus providing a possible therapeutic strategy for hepatic fibrosis." (PMID 37805473, 2023). "In KCs isolated from in vivo liver fibrosis model or in vitro M1-polarized macrophages, METTL3 was up-regulated, and sequentially, it increased MALAT1 level via m6A methylation, which promoted USP8 mRNA degradation through the interaction with PTBP1." (PMID 34839365, 2021).
lymph node metastasis (3 papers, 2017 to 2021). "More importantly, our study also showed that over-expression of PTBP1 was correlated with poor DFS with stage II (without lymph node metastasis) and stage III patients (with lymph node metastasis), respectively and independently." (PMID 28404950, 2017).
malignant glioma (3 papers, 2021 to 2022). A grade III or grade IV glioma arising from the central nervous system. "In this study, we detected the expression of PTBP1 in 150 cases of adult malignant gliomas by immunohistochemistry and evaluated its relationship with clinicopathological parameters by chi-square test." (PMID 35299889, 2022). "We explored the expression of PTBP1 protein using immunohistochemistry in 150 adult malignant glioma tissues and 20 normal brain tissues and evaluated its association with clinicopathological parameters by chi-square test." (PMID 35299889, 2022). "The median PTBP1 expression level in malignant glioma (WHO 2-4) was used as the cut-off point to divide the patients into low-PTBP1 and high-PTBP1 expression groups." (PMID 35299889, 2022). "Importantly, we analyzed the samples from our patient cohort, and found that the ratio of intron-retained/total PTBP1 is significantly lower in malignant glioma patient samples compared to normal brain samples." (PMID 34548489, 2021). "Therefore, PTBP1, as the key splicing regulator of ITSN1, should be treated as a promising therapeutic target for suppressing the progress of malignant gliomas." (PMID 36171198, 2022). "Here, our study identified that SON is highly expressed in malignant gliomas, especially in GBM, and the high level of SON promotes the removal of detained introns from the PTBP1 transcript, thereby upregulating PTBP1 expression and activating PTBP1-mediated oncogenic splicing program." (PMID 34548489, 2021).
myeloma (3 papers, 2020 to 2022). "Correlations between PTBP1 expression and clinicopathological characteristics, proliferative activity, and response to therapy of myeloma cells were analyzed." (PMID 32655719, 2020). "Given that PTBP1 is involved in PKM2 mediated-myeloma progression, we also investigated the correlation between of PTBP1 and PKM2 in MM patients." (PMID 32655719, 2020). "In this study, we investigated the impact of PTBP1 expression in MM patients' survival, as well as the correlation with clinicopathological characteristics, proliferative activity, and response to therapy of myeloma cells." (PMID 32655719, 2020). "To evaluate the potential that PTBP1 is important for MM, we examined the expression of PTBP1 in normal plasma (NP), smoldering multiple myeloma (SMM), monoclonal gammopathy of undetermined significance (MGUS), and myeloma cells using GEP datasets." (PMID 32655719, 2020).
osteoarthritis (3 papers, 2023 to 2024). A noninflammatory degenerative joint disease occurring chiefly in older persons, characterized by degeneration of the articular cartilage, hypertrophy of bone at the margins and changes in the synovial membrane. "For instance, lncRNA AC006064.4-201 destabilized CDKN1B mRNA by interaction with PTBP1, which led to alleviation of cartilage senescence and protection of osteoarthritis." (PMID 37779916, 2023).
osteoporosis (3 papers, 2022 to 2024). A condition of reduced bone mass, with decreased cortical thickness and a decrease in the number and size of the trabeculae of cancellous bone (but normal chemical composition), resulting in increased fracture incidence. "In the pathogenesis of osteoporosis, high levels of lncRNA SNHG1 increased the expression of DNMT1 via interacting with PTBP1." (PMID 38057885, 2023). "In summary, lncRNA SNHG1 upregulated the expression of DNMT1 via interacting with PTBP1, resulting in Opg hypermethylation and decreased Opg expression, which in turn enhanced BMSC adipogenic differentiation and contributed to osteoporosis." (PMID 34854215, 2022). "In sum, our study demonstrated that lncRNA SNHG1 upregulated the expression of DNMT1 via interacting with PTBP1, resulting in Opg hypermethylation and decreased Opg expression, which in turn enhanced BMSC adipogenic differentiation and contributed to osteoporosis." (PMID 34854215, 2022).
pancreatic ductal adenocarcinoma (3 papers, 2021 to 2022). An infiltrating adenocarcinoma that arises from the epithelial cells of the pancreas. "In addition, upregulation of PTBP1 has been implicated in acquired resistance to the chemotherapeutic agent gemcitabine in pancreatic ductal carcinoma cells." (PMID 36138008, 2022). "In Pancreatic ductal adenocarcinoma cells, the regulation of PTBP1 on pyruvate kinase gene alternative splicing affects the therapeutic effect of gemcitabine." (PMID 35962324, 2022). "Similar to CRC, pancreatic ductal adenocarcinoma (PDAC) has also been shown to favor the PKM2 isoform over PKM1 secondary to PTBP1 upregulation and increased incidence of PTBP1 pre-mRNA binding, particularly in drug-resistant PDAC (DR-PDAC)." (PMID 34769221, 2021).
pulmonary arterial hypertension (3 papers, 2019 to 2020). Pulmonary arterial hypertension (PAH) is a group of diseases characterized by mean pulmonary artery pressure >20 mmHg and elevated pulmonary arterial resistance leading to right heart failure. "In patients with pulmonary hypertension, the upregulation of PTBP1 accelerates glycolysis of endothelial cells (BOECs) in blood growth, leading to abnormal metabolism and proliferation of BOECs41." (PMID 31862871, 2019). "They showed that heritable pulmonary arterial hypertension (HPAH) and idiopathic pulmonary artery hypertension (IPAH) BOECs exhibited increased expression of PTBP1 and PKM2, and a shift from oxidative phosphorylation to aerobic glycolysis." (PMID 32466553, 2020).
type 2 diabetes (3 papers, 2012 to 2020). "Increased nuclear retention of PTBP1 in the islets of individuals with type 2 diabetes may also contribute to impaired glucose-stimulated insulin biosynthesis." (PMID 32894308, 2020). "Of interest, PTBP1 seems to be involved in impairment of this mechanism in type 2 diabetes." (PMID 23077502, 2012). "Furthermore, common polymorphisms within PTBP1 influence glucose-stimulated insulin secretion, albeit, in general, PTBP1 mRNA levels in the islets of individuals with impaired glucose tolerance and type 2 diabetes are unaffected as compared with individuals with normoglycaemia." (PMID 32894308, 2020).
adenoma (2 papers, 2016 to 2017). A neoplasm arising from the epithelium. "We examined the expression level of PTBP1 in 30 cases (25 cancer and 5 adenoma samples), which were also used for Western blotting analysis." (PMID 26980745, 2016). "The PTBP1 expression was more up-regulated in the adenocarcinoma than in the high-grade adenoma when each expression was compared with that in the normal tissue." (PMID 26980745, 2016). "Interestingly, PTBP1 expression was already up-regulated in all adenoma samples tested." (PMID 26980745, 2016). "PTBP1 expression levels were determined by using immunohistochemical analysis in 202 CRC, 44 adenomas and 106 normal colonic epitheliums." (PMID 28404950, 2017). "In addition, PTBP1 displayed the more frequent strong immunoreactivity in 77.2% of adenomas with or without atypical hyperplasia, similar with the result in CRC (56.3%)." (PMID 28404950, 2017).
asthma (2 papers, 2023 to 2024). "According to the insights extracted from data and the profound effect of the PTBP1 in severe asthma and its susceptibility to various stressors such as obesity and hypoxia, we selected 55 association rules in which the PTBP1 appeared as the antecedent part." (PMID 37717070, 2023). "The PTBP1 was the most frequent itemset with 16 repeat counts in asthmatic association rules; it also appears to be impactful in steering moderate asthma to severe asthma." (PMID 37717070, 2023). "PTBP1 was the gene most frequently associated with severe asthma among candidate genes." (PMID 37717070, 2023). "PTBP1 plays an important role in the humoral immune response and PTBP1 deletion in dendritic cells has been shown to enhance asthma exacerbation." (PMID 38540988, 2024). "The top 20 genes including the PTBP1, RAB11FIP3, APH1A, and MYD88 were recognized as the most frequent items among severe asthma association rules." (PMID 37717070, 2023). "PTBP1 can significantly affect airway inflammation and remodeling in asthma by modulating the PI3K/PTEN/AKT/mTOR/HIF-1/VEGF signaling pathways." (PMID 37717070, 2023). "Based on our results, the PTBP1 [polypyrimidine tract-binding protein 1; also known as hnRNP1 (heterogeneous nuclear ribonuclear protein I)] ranked as the 1st important gene in mediating severe asthma." (PMID 37717070, 2023). "Given the roles of PTBP1 in the regulation of different processes of immune cells, its impairment may lead to immune dysregulation in asthma." (PMID 37717070, 2023). "To date, there is a lack of reports linking the PTBP1 with asthma and obesity." (PMID 37717070, 2023).
autoimmune disease (2 papers, 2023 to 2024). A disorder resulting from loss of function or tissue destruction of an organ or multiple organs, arising from humoral or cellular immune responses of the individual to their own tissue constituents. "The caspase 3-resistant PTBP1 knock-in mice demonstrated that deregulation of Y RNA cleavage or/and PTBP1 truncation in apoptosis is involved in deregulation of the immune system, possibly causing the generation of autoantigens, leading to the development of autoimmune diseases." (PMID 38997262, 2024). "Since alternative splicing of RNAs has vital roles during the maturation and activation of immune cells, abnormal splicing due to PTBP1 dysregulation can trigger autoimmune diseases." (PMID 37717070, 2023).
cardiac hypertrophy (2 papers, 2023 to 2024). "Moreover, recent studies have demonstrated that the overexpression of PTBP1 was sufficient to induce cardiac hypertrophy and diastolic dysfunction." (PMID 39045460, 2024). "The overexpression of PTBP1 can induce cardiac hypertrophy and exacerbate cardiac fibrosis, either by disrupting alternative splicing or by reducing mRNA stability, while the knockdown of PTBP1 improves cardiac fibrosis in the MI-injured mouse heart, indicating a potential role in cardiac repair." (PMID 37569379, 2023).
Depression (2 papers, 2022 to 2023). "The sample area was the prefrontal cortex, and because no human samples were analyzed for comparison in the current study, there was no experimental verification of whether the differential gene expression, including Ptbp1, is associated with depression pathogenesis." (PMID 35711916, 2022). "Nevertheless, the results of the current study suggest that in a mouse model of depression (BDNF+/−), CXCL1 deletion and Slc17a7 reduction are related to the loss of excitatory neurons in the prefrontal lobe, whereas Ptbp1 downregulation correlates with neuronal regeneration." (PMID 35711916, 2022).
hypopharyngeal carcinoma (2 papers, 2025). Carcinoma, predominantly squamous cell, arising from the epithelial cells of the hypopharynx. "The journal retracts the article “HOXA11-AS1 promotes PD-L1–mediated immune escape and metastasis of hypopharyngeal carcinoma by facilitating PTBP1 and FOSL1 association”, cited above." (PMID 40488559, 2025).
Insulin resistance (2 papers, 2022 to 2024). Increased resistance towards insulin, that is, diminished effectiveness of insulin in reducing blood glucose levels. "Mutant Reg1cp increased insulin resistance via inhibiting polypyrimidine tract binding protein 1 (PTBP1) phosphorylation and the PTBP1-AdipoR1 pathway." (PMID 38390204, 2024).
ischemic stroke (2 papers, 2025 to 2026). A stroke disorder caused by obstruction of blood flow to the brain, due to thrombotic (local blood clot formation) or embolic (due to a blood clot or other material traveling from another site) event. "Further analysis revealed that exposing astrocytes to oxygen-glucose deprivation (OGD), a model for ischemic stroke, significantly reduced circSCMH1 levels, while Ptbp1 levels increased over time, peaking at 6 hours post-treatment." (PMID 41328340, 2026). "Ischemic stroke induced substantial PTBP1 upregulation in peri-infarct zones, as demonstrated in our study." (PMID 41328340, 2026). "The study identifies the specific binding domains and demonstrates that downregulating PTBP1 restores circSCMH1 levels, reduces astrocyte activation, and enhances functional recovery after ischemic stroke." (PMID 41328340, 2026). "This research unveils a novel regulatory mechanism in ischemic stroke, highlighting how PTBP1 upregulation, especially in astrocytes, inhibits the biogenesis of circSCMH1 by binding to its precursor." (PMID 41328340, 2026). "Following an ischemic stroke, the expression of PTBP1 is significantly upregulated, particularly in astrocytes." (PMID 41328340, 2026). "Additionally, our study demonstrated that PTBP1 is highly expressed in astrocytes following ischemic stroke, elucidating the specific molecular mechanism responsible for the reduction of circSCMH1 in astrocytes." (PMID 41328340, 2026).
left ventricular noncompaction (2 papers, 2023 to 2024). Left ventricular noncompaction (LVNC) is a rare cardiomyopathy characterized anatomically by prominent left ventricular trabeculae and deep intratrabecular recesses causing progressive systolic and diastolic dysfunction, conduction abnormalities, and occasionally thromboembolic events. "The endothelial-specific knockout of Ptbp1, in either endocardial cells or pan-endothelial cells, leads to a typical phenotype of left ventricular noncompaction (LVNC)." (PMID 37002228, 2023).
liver disease (2 papers, 2021 to 2023). "It has been reported that PTBP1 interacts with diverse lncRNAs and is implicated in various liver diseases." (PMID 37805473, 2023).